TLR4 (toll like receptor 4)
Diseases named in the same sentence as TLR4 in open-access papers (continued):
Sharing a sentence is not in itself a finding about the gene and the disease.
tumor (continued). "Actinomyces triggers the expression of several microbial- and immune-related genes, including TLR2, TLR4, and NF-κB, which promote CRC development by regulating inflammation and anti-tumor immunity." (PMID 36119074, 2022). "TLR4−/− mice were also resistant to tumor-driven browning of WAT, indicating direct involvement of TLR4 signaling in the metabolic reprogramming in WAT, including lipolysis and browning." (PMID 35646636, 2022). "In this study, we noted elevated expressions of TLR4, NF-κBp65, and HIF-1α in EOC specimens, and their expressions were significantly correlated with the histological differentiation degree of the tumor." (PMID 35464826, 2022). "hPRDX5 was shown to play the anti-tumor effect by regulating the populations of immune cells and immunosuppressive cells in the TME and activate NK cells most likely via the TLR4 signaling pathway." (PMID 36102418, 2022). "Mouse hepatocytes that express HCV-NS5A in liver upregulate the expression of Toll-like receptor 4 (TLR4) and develop liver tumors containing NANOG positive, tumor-initiating stem-like cells (TICs)." (PMID 36187761, 2022). "HMGB1, which is passively released by dying cells during ICD, binds to Toll-like receptor 4 (TLR4) on DCs, resulting in the efficient cross-presentation of antigens from the dying tumor cells." (PMID 36497086, 2022). "Lastly, NAM treatment regulated neuroinflammation by reducing Toll-like receptor 4 (TLR-4), phosphorylated nuclear factor-κB, tumor (p-NFκB), and cyclooxygenase-2 (COX-2) levels by 0.5- to 2-fold in the PD mouse brain." (PMID 36428497, 2022). "HMGB1, released from dying cancer cells, binds with TLR4 expressed on DCs to strengthen the antigen-presenting activity of DCs through activating the PI3K/AKT/mTOR signaling pathway, and promotes anti-tumor immune response of T cells." (PMID 36703971, 2022). "Upon re-establishment of portal blood flow, bacterial LPS activated the Toll-like receptor 4 (TLR4) signaling pathway in the liver, leading to aggravated IRI, exacerbated inflammatory response, and increased tumor burden." (PMID 35634295, 2022). "Our study demonstrated a novel molecular mechanism behind LPS‐mediated tumor regression that involves the transcriptional regulation of tumor suppressor SMAR1 by TOPORS, a zinc finger binding transcription factor via TLR4‐TRIF axis." (PMID 34689394, 2022). "On the one hand, CRT is an ‘eat me’ signal that triggers the phagocytosis of dying tumor cells by DCs, whereas HMGB1 binds to TLR4 and promotes DC maturation and tumor antigen presentation to CTLs." (PMID 35335881, 2022). "Previously, miR-26a was shown to suppress tumor growth and metastasis formation by targeting the IL-6/STAT3 pathway and modulate the neuroinflammatory response induced by TLR4 stimulation." (PMID 36499093, 2022). "Tumor HMGB1 and TLR4/RAGE receptors promote cell proliferation, survival, migration, epithelial-to-mesenchymal transition, and apoptosis resistance involving interaction with β-catenin, Runx2, YAP1, and TGF-β1/Smad." (PMID 33669632, 2021). "CD180 is a LPS receptor similar to Toll-like receptor 4 (TLR4) and is reported to promote oncogenesis and tumor growth." (PMID 34864816, 2021). "Some studies have shown that HSPA1A can enhance the apoptosis resistance of H22 cells to promote tumor growth by activating NF- κB, and HSPA1A of extracellular to the endogenous ligand of TLR4 and TLR2." (PMID 34059060, 2021). "Debris from necrotic PDAC cells induced IL-1β production by M2 macrophages through the TLR4/TRIF/NF-κB signaling pathway, which was further enhanced by tumor-derived IgG from PDAC cells including PANC-1 and BxPC-3." (PMID 34226529, 2021). "Herein, we investigate the effect of BCG tumor treatment in TLR2−/−, TLR4−/−, TLR7−/− and TLR9−/− mice." (PMID 34341449, 2021). "M3G specifically activated TLR4 in NSCLC cells and upregulated PD-L1 expression through the PI3K signaling pathway, thereby inhibiting CTL cytotoxicity and finally promoting tumor immune escape." (PMID 33628591, 2021).
tumor (continued). "LPS can also regulate TLR4 to induce IL-6 response through MAPK and PI3K pathways, which promote tumor progression." (PMID 34141706, 2021). "Overall, the current study showed that M3G activated TLR4 in NSCLC cells and upregulated PD-L1 expression through the PI3K signaling pathway, thereby inhibiting CTL cytotoxicity and finally promoting tumor escape from the immune system." (PMID 33628591, 2021). "In this study, we determined the efficacy of TLR4 antagonist TAK-242 in regulation of UVB-induced DNA damage, inflammation, and tumor development." (PMID 34771569, 2021). "We have shown that the commonly used chemotherapeutic combination of GEM and DOX can influence tumor infiltrating lymphocytes when combined with a potent TLR4 agonist, MPLA, in the aggressive 4T1 tumor model." (PMID 33532588, 2021). "We evaluate BCG intratumoral treatment in a subcutaneous MB49 tumor model using different knockout (KO) mice (STING−/−, cGAS−/−, TLR2−/−, TLR3−/−, TLR4−/−, TLR7−/−, TLR9−/−, TLR3/7/9−/−, MyD88−/−, IL-1R−/−, Caspase1/11−/−, Gasdermin-D−/− and IFNAR−/−)." (PMID 34341449, 2021). "In vitro, the protein HMGB1 promotes NET formation through a TLR4-dependent manner and in vivo, inhibition of both HMGB1 and NETs significantly delays tumor growth." (PMID 33986291, 2021). "Circulating HMGB1 promotes dendritic cell maturation and activation via Toll-like receptor 4 (TLR4), which facilitates the cross-presentation of shed tumor antigens by dendritic cells to activate tumor-specific cytotoxic T cells." (PMID 33799527, 2021). "Our studies, in the past decade, on the role of TLR4 in regulation of UVB-induced DNA damage, immune suppression and tumor development have paved the way for pre-clinical studies in this area from our group and others." (PMID 34771569, 2021). "Arctium lappa L. root extract with cytotoxicity effect on cancer cell lines enhances apoptosis and up-regulates the expression of TLR-4 and AKT/ERK in the downstream pathway of the TLR-4 cell signaling and decreases tumor cells adhesion." (PMID 34904014, 2021). "The TLR4 inhibitor, TAK-242, attenuated ERG-mediated migration, clonogenic survival, target gene activation and tumor growth." (PMID 33554122, 2021). "Other studies have demonstrated that glucocorticoids interfere with anti-tumor immune response by downregulating MHCII and TLR-4." (PMID 33918733, 2021). "Due to the ability of biglycan to affect ROS production via TLR2 and TLR4 in a NOX1- and NOX4-dependent manner, it is very likely that biglycan potentially influences tumor angiogenesis via ROS level regulation." (PMID 34917515, 2021). "Lipid accumulation in TAMs thereby promotes CB2/TLR4-dependent macrophage activation, inhibition of CD8+ T cells and thus tumour progression." (PMID 34830856, 2021). "DAMPs displayed by the tumor cell, HMGB1 and calreticulin, interact with their receptors on DCs, toll-like receptor 4 (TLR4) and CD91 (cluster of differentiation 91), respectively." (PMID 34298632, 2021). "Meanwhile, IL-10, TGF-β, TLR4, MYD88 and NF-κB in tumor tissue were increased, indicating that the LC model of mouse was successfully developed." (PMID 33967748, 2021). "The considerable CXCL1-induced up-regulation of TLR4, TNFSF10/TRAIL, and KITLG expression along with MICA/MHCI down-regulation, enable tumor evasion from immune surveillance." (PMID 34195201, 2021). "Others suggested that Salmonella is able to promote T helper 1 polarization through Toll-like receptor 4 (TLR-4), and this in turn contributes to Salmonella-mediated tumor inhibition." (PMID 34203478, 2021). "In KIRC, the results suggested that the mRNA levels of TLR1, TLR2, TLR3, TLR4, TLR7, and TLR8 were elevated in tumour tissues compared with normal kidney tissues." (PMID 34531911, 2021).
tumor (continued). "Simultaneously, the circulatory and hepatic monocytic MDSCs were significantly decreased in CXCL10−/− (circulatory: p = 0.0098; hepatic: p = 0.0213) and TLR4−/− (circulatory: p = 0.0134; hepatic: p = 0.0247) mice of IRH with tumor recurrence model." (PMID 33990548, 2021). "TLR4 inhibition and Abx treatment during the inflammatory phases of CAC potently decreased tumor growth, probably through the reduction of chronic inflammation." (PMID 34025672, 2021). "TLR4-primed MSCs are called MSC1 that exhibited an antitumorigenic impact, while TLR3-primed MSCs are called MSC2 that had a tumor-supportive function." (PMID 34736460, 2021). "There was a significant delay in tumor growth with reduced tumor incidence and weight in DKO mice versus WT, while single Tlr2–/– and Tlr4–/– mice presented an intermediate phenotype." (PMID 34032639, 2021). "Tenascin-c, a glycoprotein whose level increases in the tumour ECM, also helps trap T-cells in the stroma by binding to Toll-like receptor 4 (TLR-4) and inducing the upregulation of CXCL12 expression." (PMID 34771746, 2021). "Knockout or inhibition of CXCL10/TLR4 signaling significantly reduced the tumor growth with decreased monocytic MDSCs and MMP14 in the mouse tumor recurrent model." (PMID 33990548, 2021). "For instance, during RT (or chemotherapy), dendritic cells (DCs) require signaling through Toll-like receptor 4 (TLR4) for efficient processing and cross-presentation of antigen from dying tumor cells (releasing HMGB1)." (PMID 34079557, 2021). "To understand how TLR4 promoted CRC growth under HFD, we examined the tumor-infiltrating immune cell profiles in the mice that had tumor TLR4 activity inhibited by C34." (PMID 34385421, 2021). "Other studies showed microbiota-induced activation of TLR4 and TLR7 resulting in pro-tumorigenic immunosuppressive TME in early and progredient tumor stages TLR5 has been described to be upregulated in TME macrophages, and to be related to tumor growth." (PMID 34298645, 2021). "Recently, we used an orthotopic grafting murine model of breast cancer to demonstrate that the tumor-derived tenascin-C is able to switch the phenotype of TAM towards a M2-like, pro-tumoral polarization, in a FBG/TLR4 dependent fashion." (PMID 33718177, 2021). "Except for TGCT and UCEC, the expression of TLR4 gene in KIRC, SKCM and STAD tumor stages is consistent with the results of previous studies." (PMID 34631699, 2021). "Previous reports indicate that tumor cells express RAGE, TLR-2, and TLR-4 to promote HMGB1-induced tumor growth." (PMID 34966671, 2021). "In the present study, we compared the expression levels of TLR4 and the classic opioid receptor, MOR, in NSCLC tumor tissues." (PMID 33628591, 2021). "Herein, we decided to investigate the role of four different MyD88-dependent single TLRs (TLR2−/−, TLR4−/−, TLR7−/− and TLR9−/−) in BCG tumor treatment." (PMID 34341449, 2021). "The activation of TLR4 in macrophages promoted intestinal inflammation in IBD and subsequent tumor development." (PMID 33995655, 2021). "The results revealed that the expression of TLR4 gene in KIRC, TGCT, UCEC, SKCM and STAD has different degrees of correlation with tumor infiltrating immune cell subsets." (PMID 34631699, 2021). "For instance, HSPA1A promotes hepatoma cell proliferation through TLR2 and TLR4 signaling pathways, and HSPA1L/HIF-1 α/GP78 significantly influences tumor progression." (PMID 34059060, 2021). "On the other hand, decreased MAGL activity in macrophages in the tumour microenvironment resulted in activation of CB2 receptor binding and inactivation of TLR4 via increased 2-AG concentration." (PMID 34830856, 2021). "Galectin-9 expression in cancer cells lacking functional TLR4 could still be triggered by HMGB1 indirectly via induction of TGF-β expression in TLR4-positive myeloid cells (e.g. tumour-associated macrophages) present in the tumour microenvironment." (PMID 34234778, 2021).
tumor (continued). "Our approach was to combine MPLA, a potent TLR4 agonist, with a chemotherapeutic combination of DOX and GEM to further amplify the tumor immune response." (PMID 33532588, 2021). "To separate direct GLA effects on tumor cells from effects of GLA on immune cells in the TME, we pretreated A20 WT cells or A20 TLR4 k.o. cells with GLA-AF (5 μg /ml) in vitro for 48 h prior to subcutaneous implantation." (PMID 32974162, 2020). "It is recognized that although we have shown that both the direct effect of TLR4 agonist on tumor cells and CD8 T cell-mediated immune effects are necessary for the anti-tumor effects of GLA, a clear distinction between the two needs further investigation." (PMID 32974162, 2020). "The abrogation of rapid endocytic uptake of fetuin‐A by the TLR4 inhibitor, CLI‐095 as well as knockdown of the receptor in tumor cells, demonstrates that TLR4 plays a central role in the physiological functions of fetuin‐A particularly in tumor cells." (PMID 33073533, 2020). "Although we found that HMGB1 was increased expressed in bevacizumab resistance tumor in vivo, a link between HMGB1 and TLR4 still unproved." (PMID 33214550, 2020). "Tumor cell-released autophagosomes (TRAPs), a type of LC3-II + double-membrane exocellular vesicles, depend on TLR4-mediated MyD88–p38–STAT3 signaling." (PMID 33505964, 2020). "The anti-tumorigenic M1 phenotype is typically acquired after stimulation with Toll-like receptor 4 (TLR4) ligands and IFN-γ, whereas the tumor-supportive M2 phenotype occurs after IL-4, IL-10 or IL-13 exposure." (PMID 32396873, 2020). "As outlined in the previous section, not only does HMGB1 bind platelets via TLR4, it also activates TLR9-dependent pathways in cancer cells, thereby promoting tumor cell proliferation, adhesion, migration and invasion after surgical stress." (PMID 33353113, 2020). "In a similar fashion, lipopolysaccharide (LPS), known as an TLR4 agonist, can be used alone or in combination with IFN-γ to switch the polarisation of macrophages towards a M1 phenotype in order to induce anti-tumour response." (PMID 32635552, 2020). "We next analyzed gene expression of TLR4 and IGF-1, both known to be expressed by tumor-infiltrating mononuclear cells and to a certain extent by tumor cells." (PMID 32425932, 2020). "In fact, DAMP proteins binding to TLR4 (e.g., HMGB1, S100, HSPs, API5, and RPS3) have been used as adjuvants for DC-based vaccines, affecting tumor prevention, treatment, and survival." (PMID 33299138, 2020). "TLR4, iNOS, IL-6, MIP-3α and VEGF were highly expressed in the transplanted tumor tissues from the LPS groups, and their expression levels were decreased in the TLR4-silenced groups." (PMID 32095158, 2020). "We found that TLR4 and AR were expressed more highly in HCC tumor tissue than in adjacent liver tissue, and we found that the expression of TLR4 was positively correlated with AR in HCC tumors (R=0.6348, P=0.026)." (PMID 31956356, 2020). "When LPS binds to TLR4 in gastric epithelial cells, the activation of TLR4 signaling induces the synthesis of inflammatory mediators including TNF-α and IL-8, which are key factors promoting subsequent tumor development." (PMID 33217986, 2020). "Future studies on targeted CSC therapy can focus more on K19, CD90, CD44, Toll-like receptors 4 (TLR4), SRY-related HMG-box gene 12 (SOX12), and aldehyde dehydrogenase (ALDH) to inhibit tumor metastasis." (PMID 32210805, 2020). "HIF-1 can deregulate TLR3 and TLR4 in OSCC cell lines under hypoxia stress, leading to potent effects on tumor cell survival, proliferation, and metastatic potential." (PMID 35047983, 2020). "HMGB1 then binds to platelets via toll-like receptor 4 (TLR4) to mediate cell adhesion and enables tumor cell survival and metastasis." (PMID 33353113, 2020).
tumor (continued). "Podoplanin (PDPN, tumor cells): CLEC-2 (platelet) and HMGB1 (tumor cells): TLR4 (platelets) are other adhesion protein-ligand pairs that support platelet activation and aggregation on tumor cells, and ultimately metastasis." (PMID 33042789, 2020). "As part of the anti-tumor immune response, DAMP-induced TLR4 activation triggers the production of pro-inflammatory cytokines, chemokines, and effector molecules." (PMID 32426283, 2020). "The extracellular S100A9 protein also acts as a ligand and interacts with surface receptors on tumor cells, including the receptor for advanced glycation end product (RAGE), Toll-like receptor 4 (TLR4) and CD147." (PMID 33203795, 2020). "Loss of function polymorphisms in TLR4 or P2RX7 fail to impact clinical outcome in patients with non-small cell lung cancer, suggesting that tumor biology, chemotherapeutic agent, or both may influence whether tumor cell death is immunogenic, and which cell death pathway is activated." (PMID 32423420, 2020). "For example, CpG oligodeoxynucleotides that mimic bacterial DNA acts as a PAMP to trigger a TLR9-dependent TLR4 activation and tumor necrosis factor (TNF)-α production by tumor-infiltrating myeloid-derived cells." (PMID 32817793, 2020). "There is adequate evidence clarifying that the modulant of TLR-4 proves efficiency and safety for GBM treatment based on previous trials concerning different neoplasms." (PMID 32354122, 2020). "Multiple investigations have revealed that activated Toll-like receptor 4 (TLR4) and the nuclear factor-κB (NF-κB) signaling pathways are involved in elevations of LPS-induced metastasis in each process, including tumor cell adhesion and invasion." (PMID 32158615, 2020). "The shortest width and longest diameter of the transplanted tumors in the nude mice were measured every 3 days.TLR4, IL-6,iNOS, IL-8,COX-2, MIP-3α, TGF-β1 and VEGF expression levels in the transplanted tumor tissue were detected by immunohistochemistry." (PMID 32095158, 2020). "Elevated S100A9 in tumor microenvironment released from cancer cells, inflammatory cells, or MDSCs fuels RAGE- dependent p38 MAPK signaling cascade and also the TLR4-dependent NF-κB signaling cascade." (PMID 33117687, 2020). "After the tumor mass was established, the mice were vaccinated with either RPS3 treated wild type or TLR4−/− DCs pulsed with E7 peptide once a week for two weeks." (PMID 30819254, 2019). "LPS injected intratumorally in a glioblastoma model induced near-complete subcutaneous tumor elimination in wild-type BALB/c mice and a 50% reduction in TLR4 knockout mice." (PMID 31240216, 2019). "In this study, we also demonstrated that RPS3 is released from tumor cells following treatment with an anti-cancer drug, and that this released RPS3 can affect the surrounding DCs expressing TLR4 in the tumor microenvironment." (PMID 30819254, 2019). "The tumor-suppressor activity of miR-6869-5p was supported by direct targeting of TLR4, subsequently inhibiting TNF‐α and IL-6 production in CRC cells via the TLR4/NF-κB signaling pathway, leading to a decrease in cellular proliferation." (PMID 31737071, 2019). "Based on previous studies, the intracellular protein HMGB1 is known to be secreted from tumor cells following chemotherapy or radiotherapy, and it is also known that HMGB1 can bind to TLR4 on DCs and activate downstream signaling pathways." (PMID 30819254, 2019). "RPS3 was released from tumor cells following treatment with an anticancer drug, and it was shown that the released RPS3 binds to TLR4." (PMID 30819254, 2019). "It was demonstrated that HSP72 and HSP105 expressed on the surface of tumor-derived EVs promoted DCs to produce high levels of pro-inflammatory cytokines (IL-6, PGE2, IL-1β, TNF-α) in a TLR2- and TLR-4–dependent manner." (PMID 31680949, 2019). "In fact, a correlation between the chronic activation of TLR4 and the progress of CRC through the release of immunosuppressive factors which promote tumor escape has been widely shown." (PMID 31186484, 2019).